AHSP (alpha hemoglobin stabilizing protein)
Description:
Acts as a chaperone to prevent the harmful aggregation of alpha-hemoglobin during normal erythroid cell development. Specifically protects free alpha-hemoglobin from precipitation. It is predicted to modulate pathological states of alpha-hemoglobin excess such as beta-thalassemia.
Synonyms: EDRF; ERAF
Tractability: Small molecule: a structure with a bound ligand is known.
Gene: Protein-coding gene on chromosome 16 (31,527,876 to 31,528,803, forward strand). Ensembl gene ENSG00000169877.
Subcellular location: Cytoplasm
Gene Ontology:
Molecular function: protein binding; hemoglobin binding
Biological process: erythrocyte differentiation; hemoglobin metabolic process; hemopoiesis; protein folding; protein stabilization
Cellular component: cytoplasm; hemoglobin complex
Genetic constraint (gnomAD): Loss-of-function variants: 5 observed, 2.86 expected, observed/expected ratio (o/e) 1.75, 90% interval 0.77 to 1.95. That is too few expected variants to judge how well the gene tolerates losing a copy. Missense variants: 134 observed, 124.81 expected, observed/expected ratio (o/e) 1.07, 90% interval 0.93 to 1.24. Synonymous variants: 50 observed, 51.3 expected, observed/expected ratio (o/e) 0.97, 90% interval 0.78 to 1.23.
Homologues: Orthologues: chimpanzee AHSP (100% identical), macaque AHSP (92% identical), rabbit AHSP (72% identical), rat Ahsp (67% identical), mouse Ahsp (64% identical), pig AHSP (61% identical), dog AHSP (44% identical).
Diseases named in the same sentence as AHSP in open-access papers:
AHSP is named in the same sentence as 20 diseases in open-access papers, as found by Europe PMC text mining. Sharing a sentence is not in itself a finding about the gene and the disease. The quoted sentences say what the papers report.
thalassemia (5 papers, 2011 to 2022). An inherited blood disorder characterized by a decreased synthesis of one of the polypeptide chains that form hemoglobin. "In addition, other modifiers were also shown to affect thalassemia phenotype, such as mutations in the molecular chaperone haemoglobin stabilizing protein (AHSP) and transcription regulator GATA1." (PMID 34650160, 2021). "Phe GH5 mutations in human α globin include Hb Foggia (Phe117α- > Ser) exhibiting a phenotype typical of α thalassemia and was found to impair interactions with both β globin and the Alpha-Hemoglobin Stabilizing Protein (AHSP)." (PMID 24655798, 2014). "However, convincing evidence of the pathological overexpression of AHSP in thalassemia cells has proven elusive, perhaps because it is a secondary compensatory response or due to the extensive genetic heterogeneity within this gene and its regulators." (PMID 35092867, 2022). "Therefore, it is likely that the combined effects of multiple signaling pathways are responsible for the overexpression of AHSP and its protective effects in thalassemia cells." (PMID 35092867, 2022). "The altered expression or function of AHSP might be related to the severity of thalassemia." (PMID 34435051, 2021). "On the other hand, αHb mutations may also result in impaired AHSP-αHb interactions and could be responsible for thalassemia-like phenotypes without explanation in some patients." (PMID 21490703, 2011).
hemoglobinopathies (3 papers, 2018 to 2024). "We found a trans-pQTL in this locus for AHSP α hemoglobin stabilizing protein (AHSP) that is associated with RBC width and mean corpuscular volume as well as phecodes related to anemia and hemoglobinopathies." (PMID 39316441, 2024). "VPA and other HDACs have been investigated for effects on hemoglobinopathies in the past and a recent preclinical study showed that 0.5 mM VPA treatment could increase Alpha Hemoglobin Stabilizing Protein (AHSP) expression in a human erythroleukemia cell line." (PMID 32642660, 2019).
anemia (2 papers, 2020 to 2024). A reduction in the number of red blood cells, the amount of hemoglobin, and/or the volume of packed red blood cells. "Much of AHSP’s function was studied in hereditary anemia; it has not been considered in other anemia such as anemia of inflammation/critical illness, which is refractory to erythropoietin administration." (PMID 32629835, 2020).
Obesity (2 papers, 2012 to 2019). Accumulation of substantial excess body fat. "An increase of up-regulated genes selectively expressed in erythrocytes/reticulocytes (including ALAS2 and ERAF/AHSP, and many other EDS genes) in whole blood was also noted to be consistent with previous observations of higher red blood cell counts (hematocrit) in obesity." (PMID 22545094, 2012).
Sepsis (2 papers, 2019 to 2023). Sepsis is defined as life-threatening organ dysfunction caused by a dysregulated host response to infection. "In heme-Hb metabolic pathways, we also identified AHSP, which is a small protein that binds specifically to the α Hb subunit, as an up-regulated gene in sepsis." (PMID 36820206, 2023). "We conclude that the heme and hemoglobin metabolism is modulated during sepsis, with emphasis in the four genes ALAS2, AHSP, HBD, and CA1, common to the three datasets." (PMID 31396396, 2019). "Thus, four common genes were found upregulated in the three datasets (ALAS2, AHSP, HBD and CA1), notably, they were most significantly expressed in follow-up samples of patients who survived sepsis." (PMID 31396396, 2019).
hemochromatosis (1 paper, 2018). A disorder of iron metabolism characterized by a triad of HEMOSIDEROSIS; LIVER CIRRHOSIS; and DIABETES MELLITUS. "The impact of hemochromatosis (HFE), glucuronosyltransferase family 1 member A1 (UGT1), and α-hemoglobin stabilizing protein (AHSP) variants needs to be clarified on the phenotype of HbH disease." (PMID 29115104, 2018).
liver carcinoma (1 paper, 2022). An epithelial or non-epithelial malignant neoplasm that arises from the liver. "Interestingly, enriched MafK signals at the MARE-1 site were found in lung A549 lung and HepG2 liver carcinoma cells, implying potential regulation of the AHSP gene by other CNC-bZIP family members." (PMID 35092867, 2022).
infection (1 paper, 2025). The state of being infected such as from the introduction of a foreign agent such as serum, vaccine, antigenic substance or organism. "Heme/hemoglobin metabolism was enriched in groups 1, 2, and 4, with four common genes (ALAS2, AHSP, HBD, and CA1) that are associated with the immune response to infection." (PMID 41839673, 2025).
tumor (1 paper, 2024). "The three tumor proteins of interest (AHSP, FABP7 and TJAP1) were downregulated in the STS group and were not identified in the proteome of serum samples from GB patients." (PMID 38803161, 2024). "metascape analysis of the three tumor proteins of interest indicated that FABP7, TJAP1 and AHSP were associated with fatty‐acid transport (GO:0015908), Golgi organization (GO:0007030) and hemoglobin metabolic process (GO:0020027), respectively." (PMID 38803161, 2024). "The TCGA‐GB transcriptomic dataset was used to validate the prognostic value of the three tumor proteins of interest (AHSP, FABP7 and TJAP1) at the mRNA level." (PMID 38803161, 2024). "For tumor samples, only three of the 5422 normalized proteins displayed significant downregulation in the STS group: FABP7, TJAP1 and AHSP." (PMID 38803161, 2024).
AHSP also shares sentences with these, for which no sentence is quoted: cancer (2 papers); Hypertension (2); sickle cell disease (2); B-cell lymphoma (1); cervical cancer (1); erythroleukemia (1); intrauterine growth restriction (1); iron deficiency (1); leukemia (1); Parkinson’s (1); prion disease (1).